MIR885 (microRNA 885)
Synonyms: hsa-mir-885; MIRN885; mir-885
Gene: MicroRNA gene on chromosome 3 (10,394,489 to 10,394,562, reverse strand). Ensembl gene ENSG00000216135.
Gene Ontology:
Biological process: miRNA-mediated post-transcriptional gene silencing
Homologues: Orthologues: chimpanzee ptr-mir-885 (100% identical), macaque mml-mir-885 (100% identical), rabbit MIR885 (95% identical), pig ssc-mir-885 (92% identical).